RELB (RELB proto-oncogene, NF-kB subunit)
Diseases named in the same sentence as RELB in open-access papers (continued):
Sharing a sentence is not in itself a finding about the gene and the disease.
colitis (2 papers, 2021 to 2024). Inflammation of the colon. "Therefore, DC-intrinsic RelB deficiency moderated inflammation and acute colitis in mice." (PMID 39060515, 2024). "Taken together, we deduce that a DC-intrinsic RelB function, where Nfkb2 is dispensable, limits the accumulation of intestinal IgA+ B cells and luminal IgA, which likely foster a gut microbiome protective against experimental colitis in mice." (PMID 39060515, 2024). "Here, we show that intestinal dendritic cells from a mouse model of experimental colitis exhibit significant levels of noncanonical NF-κB signaling, which activates the RelB:p52 heterodimer." (PMID 39060515, 2024). "We found that T-cell development in vivo, TH polarization in vitro and T-cell-transfer-induced colitis did not require RelB activity." (PMID 34608221, 2021).
endometrioid adenocarcinoma (2 papers, 2016 to 2018). An adenocarcinoma characterized by the presence of malignant glandular epithelial cells resembling endometrial cells. "Increased RelB expression enhances endometrioid adenocarcinoma (EEC) cell growth by regulating cell proliferation, leading to endometrial cell tumourigenicity." (PMID 30473630, 2018). "We found that NF-κB RelB protein, but not RelA, displayed high expression in EC samples and cell lines, with predominant elevation in endometrioid adenocarcinoma (EEC)." (PMID 27711077, 2016).
fungal infections (2 papers, 2016 to 2024). "Thus, inherited human RelB deficiency disrupts the alternative NF-κB pathway, underlying a T- and B cell immunodeficiency, which, together with neutralizing autoantibodies against type I IFNs, confers a predisposition to viral, bacterial, and fungal infections." (PMID 39231201, 2024). "The correction of susceptibility to bacterial and fungal infections after successful HSCT confirms the presence of leukocyte-intrinsic defects in the absence of human RelB." (PMID 39231201, 2024).
gastric cancer (2 papers, 2020). A primary or metastatic malignant neoplasm involving the stomach. "Taken together, dysregulated RELB, IL-32, and SLC7A11 may mediate inflammatory responses, oxidative stress levels or cellular energy metabolism to potentiate the ability of H. pylori to induce gastric carcinoma." (PMID 32457731, 2020).
head and neck squamous cell carcinoma (2 papers, 2015 to 2017). A squamous cell carcinoma that arises from any of the following anatomic sites: lip and oral cavity, nasal cavity, paranasal sinuses, pharynx, larynx, and salivary glands. "In addition, a more recent study of head and neck squamous cell carcinoma proposed a combined effect of both IKKα and IKKβ on the nuclear localization of canonical RelA and alternative RelB and P100/P52 subunits." (PMID 26147201, 2015).
laryngeal carcinoma (2 papers, 2017 to 2019). Carcinoma that arises from the laryngeal epithelium. "Our simple but robust approach identifies that NF-κB subunits, especially P50 and RelB are linked with laryngeal cancer progression." (PMID 29371965, 2017). "In summary, our findings support that, pending further clinical validation, immunohistochemical assessment of RelB expression at the time of diagnosis of laryngeal cancer is intimately linked with tumor progression and can accurately predict prognosis." (PMID 29371965, 2017). "Overexpression of RelA and P50 has been previously reported in laryngeal carcinoma and has been linked to tumor progression, therapy response, and prognosis, but the potential role of RelB as a biomarker of progression and survival is still under investigation." (PMID 29371965, 2017). "Tumor grade emerged as the only independent predictor of survival, suggesting that tumor stage, local extent necessitating intervention, and RelB expression are interconnected predictors of survival in laryngeal cancer." (PMID 29371965, 2017). "Using Cox regression analyses and tumor stage, local extent, grade and RelA/RelB immunoreactivity, we develop a new score that can independently predict survival of patients with laryngeal cancer." (PMID 29371965, 2017). "Identifying the link between P50 and RelB with laryngeal cancer progression could be mechanistically explained by the fact that RelB, which is known to form dimers with P100/P52, has been recently published to form heterodimers with P50." (PMID 29371965, 2017). "We show how using this clinically relevant approach, RelB expression was found to increase with tumor stage, grade, and local extent and to portend poor survival, establishing it as a useful biomarker of prognosis in laryngeal cancer." (PMID 29371965, 2017). "Here we show that RelB expression assessed by immunohistochemistry and a simple scoring system at the time of diagnosis can be used as a cheap and accurate bedside test to predict the prognosis of patients with laryngeal cancer." (PMID 29371965, 2017). "Future studies designed to prospectively resample patients with laryngeal cancer after treatment could validate our findings and would assess the value of RelB as a potential biomarker of treatment response." (PMID 29371965, 2017).
leukemia (2 papers, 2008 to 2023). A malignant (clonal) hematologic disorder, involving hematopoietic stem cells and characterized by the presence of primitive or atypical myeloid or lymphoid cells in the bone marrow and the blood. "RelB deficiency delayed leukemia onset in the TEL-JAK2 transgenic mouse model of human T acute lymphoblastic leukemia." (PMID 18596915, 2008). "In contrast, RelB plays a role in radio-resistant stromal cells to accelerate leukemia onset and increase disease severity." (PMID 18596915, 2008). "Interestingly, we have identified the IL-15 production pathway to be activated in leukemia cells cultured in the 3D BM niche-like AML model, with different associated genes upregulated, including EGFR, IGF1R, MET, RELB, and ERBB2." (PMID 37932837, 2023). "Interestingly, bone marrow chimeric mouse experiments showed that RelB is not required in the hematopoietic compartment but plays a role in radio-resistant stromal cells to favor leukemia onset and increase disease severity." (PMID 18596915, 2008). "TEL-JAK2 leukemic cells displayed NF-κB activity (p50, p52, RelA, and RelB), suggesting that, in addition to a noncell-autonomous role, NF-κB activation may also contribute cell-autonomously to TEL-JAK2 leukemia development or maintenance." (PMID 18596915, 2008).
lung diseases (2 papers, 2014 to 2015). "Previous studies of the importance of RelB on CS and lung diseases have been restricted to experimental in-vitro and in-vivo models." (PMID 25409035, 2014).
lymph node metastasis (2 papers, 2015 to 2018). "The clinico-pathological association study demonstrated that the expression of RelB was positively correlated with depth of tumor invasion (p = 0.018), lymph node metastasis (p < 0.001), metastasis stage (p = 0.031), and pTNM stage (p = 0.001)." (PMID 30473630, 2018). "The mRNA level of RelB is correlated with bladder cancer pathological, clinical stage, and lymph node metastasis." (PMID 30473630, 2018). "Importantly, the RelB expression was correlated with depth of tumor invasion, lymph node metastasis, metastasis stage, and pTNM stage." (PMID 30473630, 2018). "Using multiple logistic regression, we identified that tumor RelB expression was an independent predictor of lymph node metastasis, and tumor P50 was an independent predictor of TNM6 stage IIB or higher, whereas tumor RelA was an independent predictor of inflammatory infiltration." (PMID 26147201, 2015). "The expression of RelB was correlated with CRC clinical stage, tumor differentiation, and lymph node metastasis." (PMID 30473630, 2018).
nephrotic syndrome (2 papers, 2021 to 2023). A collection of symptoms that include severe edema, proteinuria, and hypoalbuminemia; it is indicative of renal dysfunction. "Group 1 was characterized by major risk genes for developing LOAD (APOC1 and APOC1P1) and immune-related genes (RELB and CBLC), whereas group 2 was characterized by genes associated with kidney disorders, such as nephrotic syndrome (AXDND1, FBP1, and MIR2278)." (PMID 37386009, 2023).
Obesity (2 papers, 2019 to 2022). Accumulation of substantial excess body fat. "On the other hand, in peritoneal macrophages, obesity significantly boosted the nuclear accumulation of cRel, without exerting any effect or trend to an effect on RelA or RelB." (PMID 31316525, 2019). "Similarly, miR-126 had altered expression in obesity and may modulate CCL2 (chemokine ligand 2) through genes that encode ETS1, MAX, NFKB1, RELB, and STAT6 proteins." (PMID 36355127, 2022).
renal carcinoma (2 papers, 2023 to 2025). A carcinoma arising from the epithelium of the renal parenchyma or the renal pelvis. "Western blot analysis confirmed that overexpression of the TPM3P9 protein in renal cancer cells upregulated RELB expression." (PMID 39865075, 2025).
renal fibrosis (2 papers, 2022 to 2024). A final common manifestation of a wide variety of chronic kidney diseases characterized by glomerulosclerosis and tubulointerstitial fibrosis. "RelB is expressed in renal tubular epithelial cells and levels gradually increase with progressive fibrosis in a mouse renal fibrosis model with unilateral ureteral obstruction." (PMID 35237156, 2022). "Interestingly, the serum RelB levels from CKD patients also correlated with the intensity of renal fibrosis compared healthy controls." (PMID 35237156, 2022). "Transcription factor RELB is a member of the NF-κB family, which has been utilized not only as a promising diagnostic and monitoring biomarker in renal fibrosis but has also been attributed to promote inflammatory cytokines expression to drive disease progression." (PMID 39682753, 2024).
sarcoma (2 papers, 2016 to 2023). A usually aggressive malignant neoplasm of the soft tissue or bone. "NF-κB subunit-specific antibody-based supershift assays indicate that no p52, RelB, or cRel DNA-binding activity was detectable in irradiated human sarcoma cells." (PMID 27014915, 2016).
thymic atrophy (2 papers, 2018 to 2025). "These surprising findings have prompted us to examine other aspects of RelB deficiency including thymic atrophy and visceral inflammation that have been previously reported." (PMID 39929805, 2025). "While the exact mechanism by which the infiltrating granulocytes promote this thymic atrophy is unknown, RelB is known to repress Il1b and granulocyte extracellular traps could act as a platform for IL-1 activation." (PMID 29872433, 2018).
adenoma (1 paper, 2015). A neoplasm arising from the epithelium. "Analyses, done as for human samples, identified that RelB was overexpressed in urethane-induced hyperplastic lesions, but not in adenomas." (PMID 26147201, 2015).
allergic contact dermatitis (1 paper, 2024). An inflammatory skin condition caused by an immune response to direct contact between the skin and an allergen. "α‐Melittin‐NPs target lymph nodes and suppress allergen‐induced maturation of dendritic cells in allergic contact dermatitis mice, whereas α‐Melittin‐NPs reduce the levels of phosphorylated-RelB (pRelB) and impede the activation and proliferation of CD8+ T cells." (PMID 38318188, 2024).
Atrophy (1 paper, 2021). Any weakening or degeneration, especially through lack of use. "In accordance with and in response to the multiorgan inflammation, thymic atrophy as measured by the reduced number of total thymocytes was detected in relB-deficient mice mildly at 1 wk old and moderately at 2 wk old." (PMID 33555295, 2021).
autoimmune polyglandular syndrome type 1 (1 paper, 2024). "We then compared the overlap of autoreactive antigen enrichment (log2-fold change relative to healthy controls >1.5 in each group) between patients with AR RelB (n = 2), autoimmune polyglandular syndrome type 1 (APS-1, n = 14) and p52LOF/IκBδGOF variants (n = 12), as in a previous study." (PMID 39231201, 2024).
autoinflammatory syndrome (1 paper, 2008). A group of disorders of the innate immune system characterized by attacks of seemingly unprovoked inflammation without significant levels of either autoantibodies or autoreactive T cells more characteristic of autoimmune disease. "Moreover, RelB-deficient (relB-/-) mice display impaired secondary lymphoid organ development and suffer from an autoinflammatory syndrome that also affects organization and function of lymphoid tissues." (PMID 19087315, 2008).
B-cell neoplasm (1 paper, 2013). A group of heterogeneous lymphoid tumors generally expressing one or more B-cell antigens or representing malignant transformations of B-lymphocytes. "RelB−/− mice also spontaneously develop a multiorgan inflammatory syndrome that contributes to premature mortality, preventing long-term studies on B-cell neoplasm development." (PMID 23555623, 2013). "Beyond MM, close relation between anti-apoptotic gene expression and RelB activity has emerged in other B-cell neoplasms." (PMID 23555623, 2013). "Thus, it is likely that the prosurvival effects of RelB observed in MM may be generalized to other B-cell neoplasms, especially those addicted to NF-κB." (PMID 23555623, 2013).
bipolar disorder (1 paper, 2021). A disorder of the brain that causes unusual shifts in mood, energy, activity levels and the ability to carry out day-to-day tasks. "We first determined whether mRNA levels for family members of the NF-κB transcriptional complex, including NF-κB1, NF-κB2, and other members of the NF-κB family that contain Rel homology domains including RelA, RelB, and cRel, were elevated in the PFC of bipolar disorder subjects." (PMID 33436571, 2021).
Brain atrophy (1 paper, 2017). Partial or complete wasting (loss) of brain tissue that was once present. "A polygenic risk score of all rare variants in 3 genes (CBLC, BCAM, RELB) was associated with multifocal brain atrophy, predominantly in the temporal and bilateral frontal lobes." (PMID 28589856, 2017).
chronic cystitis (1 paper, 2015). Recurrent infections of the urinary bladder. "The p65 and RelB mRNA levels were both higher in the BCa and the chronic cystitis group compared to the healthy bladder mucosa group (both, P<0.05)." (PMID 25369740, 2015). "The mRNA level of the downstream NF-κB canonical pathway p65 gene and of the non-canonical pathway RelB gene were higher in the BCa and cystitis groups compared to the healthy one." (PMID 25369740, 2015).
Cirrhosis (1 paper, 2022). A chronic disorder of the liver in which liver tissue becomes scarred and is partially replaced by regenerative nodules and fibrotic tissue resulting in loss of liver function. "Several oncogenic transcription factors (TFs) inferred with DoRothEA35 including FOS, ETS2, RELB, SOX10, ERG, WT1 and JUND and TFs supporting stemness such as PBPJ and ARID3A were upregulated in cirrhosis patients and correlated with bacterial translocation." (PMID 35803930, 2022).
diabetic nephropathy (1 paper, 2010). "Changes in the expression of NIK and RelB, including increased cytosolic NIK and RelB expression, were found in kidneys from experimental diabetic nephropathy animals." (PMID 20126461, 2010).
epidermodysplasia verruciformis (1 paper, 2024). A rare inherited genodermatosis characterized by chronic infection with human papillomavirus (HPV) leading to polymorphous cutaneous lesions and high risk of developing non melanoma skin cancer. "Both RelB-deficient patients experienced infections related to a T cell defect: CMC (P1 and P2), C. neoformans meningitis (P1), epidermodysplasia verruciformis and recalcitrant skin warts (P2), and JC virus-induced PML (P2)." (PMID 39231201, 2024).
Epstein-Barr virus infection (1 paper, 2021). An infection that is caused by Epstein-Barr virus. "One was the Epstein-Barr virus infection pathway (q-value=0.025), represented by four upregulated genes (CDKN1A, NFKB2, RELB, and PDIA3) and two downregulated genes (BID and HLA-A)." (PMID 33785040, 2021).
food allergy (1 paper, 2024). Gastrointestinal disturbances, skin eruptions, or shock due to allergic reactions to allergens in food. "This difference was grossly maintained during food allergy and Hpb infection suggesting a stable effect of RelB on the absolute number of resident cDC2s in mLN." (PMID 39443450, 2024).
glaucoma (1 paper, 2024). Increased pressure in the eyeball due to obstruction of the outflow of aqueous humor. "Unlike RelA, RelB remained understudied in glaucoma research." (PMID 38824526, 2024).
HIV-1 infection (1 paper, 2018). The type species of lentivirus and the etiologic agent of acquired immunodeficiency syndrome (AIDS). "The result showed that RelB enhanced HIV-1 gene expression during HIV-1 infection." (PMID 30241541, 2018).
Hypervolemia (1 paper, 2023). An increase in the amount of intravascular fluid, particularly in the volume of the circulating blood. "Exact molecular analysis of the RelB action in hypervolemia is required to support our findings." (PMID 38139378, 2023).
hypohidrotic ectodermal dysplasia (1 paper, 2025). A genetic disorder of ectoderm development characterized by malformation of ectodermal structures such as skin, hair, teeth and sweat glands. "Osteopetrosis is occasionally observed in patients with XL-NEMO deficiency (OL-EDA-ID, osteopetrosis, lymphedema, hypohidrotic ectodermal dysplasia, and immunodeficiency), but not in patients with inborn errors of IKK-α, NIK, RelB, or NF-κB2." (PMID 41608125, 2025).
inflammatory bowel disease (1 paper, 2017). A spectrum of small and large bowel inflammatory diseases of unknown etiology. "The inflammation and inflammatory bowel disease (IBD) disorders had many commonly modulated genes that were also found in the String analysis that were common with the disorders which included IL-8, ICAM1, RELB, NFκBIA, TNFAIP3, LIF, CXCL1, CXCL2, CXCL3, CXCL10, and TNF-α." (PMID 28099447, 2017).
Insulin resistance (1 paper, 2022). Increased resistance towards insulin, that is, diminished effectiveness of insulin in reducing blood glucose levels. "Streptozotocin-induced diabetic rats with vitamin D deficiency had enhanced insulin resistance with high proportion of phospho-p65 (p-p65)/RelB in which RelB is an anti-inflammatory molecule, while p-p65 is a pro-inflammatory molecule." (PMID 35859985, 2022).
intraepithelial neoplasia (1 paper, 2018). A precancerous neoplastic process that affects the squamous, glandular, or transitional cell epithelium without evidence of invasion. "In intraepithelial neoplasia, a precancerous condition of the prostate also showed increased p50 subunit with other binding partners like RelB and p52 over the classic heterodimer expression supporting disease progression." (PMID 30225173, 2018).
invasive breast carcinoma (1 paper, 2018). A carcinoma that infiltrates the breast parenchyma. "Notably, RelA-dependent RelB synthesis was implicated in the activation of the RelB:p50 dimer in transformed B-cells and invasive breast cancer cells." (PMID 29772694, 2018).
liver cancer (1 paper, 2022). An epithelial or non-epithelial malignant neoplasm that arises from the liver. "There was no apparent relationship of PD-L1 with RelA or RelB in liver cancer." (PMID 35177112, 2022).
liver disease (1 paper, 2021). "Overall, the upregulation of CDKN1A, NFKB2, RELB, and PDIA3 indicates a worse prognosis of liver disease and an impaired immune response against HIV." (PMID 33785040, 2021).
liver failure (1 paper, 2025). A liver disease characterized by the liver losing or has lost all of its function. "In mice, RelA (p65) or IκBα knockouts die at embryonic or neonatal stages from liver failure or hyper-inflammation; p50, c-Rel, or p52 knockouts are immunodeficient but viable; RelB mutants succumb early to severe inflammation." (PMID 41439955, 2025).